CASP8 (caspase 8)
Diseases named in the same sentence as CASP8 in open-access papers (continued):
Sharing a sentence is not in itself a finding about the gene and the disease.
cancer (continued). "Interestingly, some studies demonstrated that the role of caspase-8 in cancer is independent of its proteolytic activity." (PMID 34482382, 2021). "Such cancers could be targeted through necroptosis, because the absence of caspase-8 or its enzymatic activity prevents the cleavage of RIPK1 and stabilizes the necrosome." (PMID 33026575, 2021). "Formononetin might induce cancer apoptosis through hydrogen-bonding with CASP3, CASP8, CASP9." (PMID 34955857, 2021). "However, the exact role of caspase-8 in the modulation of the TME in cancers is not yet fully understood." (PMID 33026575, 2021). "To determine whether ITCH-induced c-FLIPL degradation had a major role in anti-HER3 antibody-induced cancer cell apoptosis, we assessed PARP and caspase-8/3 cleavage by western blotting in siITCH and siSC BxPC3 cells incubated with 9F7-F11 alone or with NRG1 for 48 h." (PMID 31443721, 2019). "Moreover, pharmacologic blockade of TβR signaling abolished the anti-cancer effects of the SBE4-TRAIL group as evidenced by reduced cleaved caspase-8 and cleaved caspase-3 compared to the group without the inhibitor treatment." (PMID 30867058, 2019). "Further determination of the apoptotic induction showed that MA or HCD and TMX combination inhibited MDA-MB-231 and MCF-7 cancer cells by upregulating Bax and by downregulating Bcl-2 mRNA and protein expression without altering Caspase-8 and Caspase-12 expression." (PMID 30082655, 2018). "Combining LUBAC inhibition with cell death-inducing treatments might be a potentially effective approach to induce immunogenic cell death of cancer cells lacking Ripk3 and/or Caspase-8 activity." (PMID 29867129, 2018). "In agreement with our previous finding that caspase-8 enzymatic activity is not required for mediating DR5 suppression-induced cancer cell invasion, the current study further demonstrates that caspase-8 mediates TRAF2 polyubiquitination induced by DR5 suppression independent of its caspase activity." (PMID 28482915, 2017). "However, questions remain what kinetic and phenotypic determinants distinguish the FasL-Fas conjugations from most transient NK- cancer cell interactions that did not activate caspase-8." (PMID 27323411, 2016). "The revealed synergistic pro-apoptotic effect, depending on both death receptors (TRAIL-R1/DR4, TRAIL-R2/DR5) and caspases (caspase-8, -9 and -3) activation, was lethal on cancer cells but not on normal human intestinal epithelial cells (HIEC), and was inhibited by Bcl-2 expression." (PMID 26771233, 2016). "Our data illustrated that not all transient NK-cancer cell interactions that were not immediately followed by target cell death were functionally futile, as some of them were successful FasL-Fas conjugations that led to caspase-8 activation." (PMID 27323411, 2016). "The reason why cancer cells are resistant to TRAIL-induced apoptosis is not yet known, but many clinical studies have attributed TRAIL-resistance to the down-regulation of TRAIL receptors and to mutation of caspase-8." (PMID 26304927, 2015). "The Bcl-2 family of proteins is related to the caspase family of proteins in cancer cell apoptosis and treatment with UDCA increased Bax expression and reduced Bcl-2, Bcl-xL expression, thus possibly affecting the expressions of caspase-3, caspase-8, and caspase-9." (PMID 25951128, 2015). "In particular, caspase-8 (CASP8) is a crucial player in controlling the apoptosis of T lymphocytes through activation-induced cell-death and, simultaneously, a physiological homeostasis of T lymphocytes is a fundamental aspect in the immune-surveillance of cancer cells." (PMID 24465592, 2014).
cancer (continued). "Down-regulation of survivin by siRNA does not induce the activation of caspase-8 in cancer cells." (PMID 20920299, 2010). "Interestingly, by using Gepia2 web server we compared the expression levels of CASP8 and NFE2L2 genes in tumors and normal tissues from The Cancer Genome Atlas (TCGA) database; the expression of both genes is aberrantly upregulated in several cancers, including GBM." (PMID 41053176, 2025). "Similar to 2D results, despite a difference in the treatment concentration, cleaved caspase 8 and PARP expression markedly increased, whereas Mcl‐1 expression decreased upon PYR administration, indicating that PYR may induce Mcl‐1‐mediated and caspase‐dependent apoptosis in cancer cell spheroids." (PMID 40765495, 2025). "However, in the past years, several studies reported an increased expression of Caspase-8 levels in many tumors and consistently identified novel “non-canonical” non-apoptotic functions of Caspase-8 that overall promote cancer progression and sustain therapy resistance." (PMID 37444381, 2023). "The anti-cancer effects of lipid-soluble vitamins in various GBM cell lines are attributed to a diverse range of molecular mechanisms through changes in the expression of a wide range of biomarkers, of which CDK2, GFAP, p27, Bax, and CASP8 genes may have some clinical value." (PMID 35889829, 2022). "However, a more rigorous assessment of Caspase-8 expression and the corresponding stratification of patients will be of utmost importance in determining the clinical success of the CDK9-based targeted strategies in cervical and other cancer entities in the future." (PMID 36399280, 2022). "In addition, caspase-8 expression was lower in women with cancer compared to non-malignant cancer." (PMID 33919909, 2021). "Interestingly, TLR3 is localized in lysosomes and might provide a way to execute LMP in cancer cells that are defective in Caspase-8 or perhaps independent of Caspase-8." (PMID 34822366, 2021). "Intriguingly, this report suggests that the inhibition of Caspase-8, although detrimental for apoptosis induction, may enhance the sensitivity of cancer cells to DNA damaging agents, most likely independent of apoptosis, and may therefore represent a valuable therapeutic strategy." (PMID 30501030, 2018). "Indeed, Caspase-8 might become a target for new anticancer drugs if it is possible to inhibit its cancer-boosting activity without interfering with its ability to promote cell death." (PMID 28594322, 2017). "Our study showed that although ERK can be inhibited through simultaneous co-administration of these two kinds of anti-cancer agents, the formation of pro-caspase-8 homodimer was not increased, whereas pre-treatment with erlotinib could increase levels of this critical dimer." (PMID 26036637, 2015). "Available FADD and caspase-8 may recruit and stabilize TRAF2 (and perhaps other unknown proteins), resulting in the activation of ERK and JNK signaling and subsequent AP-1-dependent expression and activation of MMPs (e.g., MMP1) and final promotion of invasion and metastasis of cancer cells." (PMID 26510914, 2015). "In addition, no apparent activation of intrinsic apoptosis signaling protein caspase-9 and extrinsic apoptosis signaling protein caspase-8 were observed after Ching001 treatment (data not shown), suggesting that Ching001 induced cancer cell apoptosis is via ER stress." (PMID 23646116, 2013). "Because most anti-caspase-8 antibodies will not discriminate between caspase-8 and -8L, it is currently unclear to which extent caspase-8L may have contributed to the caspase-8 expression detected in the immunohistochemical analyses of various cancer types." (PMID 24281211, 2010). "However, the relevance of upregulated DR5 expression for enhanced TRAIL DISC formation and stress-triggered sensitization of cancer cells to TRAIL-induced apoptosis is controversially discussed, as it may also result from an enhanced binding of caspase-8 to the DISC." (PMID 18665234, 2008).
cancer (continued). "Indeed, the cell death assay results supported this notion, as a caspase 8 inhibitor did not block Bax∆2-mediated cell death in these neuronal cells, in contrast to cancer cells, suggesting that Bax∆2-SG-triggered cell death may not occur via caspase 8 in neuronal cells." (PMID 37371550, 2023). "Proteases present in malignant tumours but not in normal skin included: PGC, BAP1, caspase-8, F13A1, MMP11, MMP23, MMP25, MMP26 and granzyme-A." (PMID 35327667, 2022). "Upon internalization, TAT-FADD interacts with pro-apoptotic caspase-8 and anti-apoptotic cFLIPL protein to formulate DISC assembly in cancer cells, independent of death receptor activation to instigate downstream signaling." (PMID 32961826, 2020). "Caspase 3, Caspase 8, CAT, Bax and SOD genes expression increased compared to control (gene expression in cancer cells without any treatment)." (PMID 32295069, 2020). "The data also showed that the expression of cleaved caspase-8, -9, -3, Bax, and TUNEL-positive cells was increased in the cancer tissues of IL-32α Tg mice than in those of non-Tg mice." (PMID 25909160, 2015). "Within the constraints of an exploratory design, JTT was associated with a significant reduction in NK-cell CD95 in vivo and a selective attenuation of Fas-mediated apoptosis downstream of caspase-8 in T cells in vitro, without affecting intrinsic apoptosis or TRAIL-induced cancer-cell apoptosis." (PMID 41304903, 2025). "Analysis of activated caspase 8 protein indicated an increase only in the sample of CIMVs-TRAIL (6.46 ± 0.8%) (n = 3, *** p < 0.001), but not the rest of the cancer cells cultured with native CIMVs (3.7 ± 0.4%), CIMVs-BFP (3.5 ± 0.7%) or without treatment (3.3 ± 0.2%)." (PMID 36661524, 2023). "Moreover, the cytotoxic effect of BSE on cancer cells was significantly reverted by Nec-1 pretreatment, and BSE induced TNF-α and RIP-1 expression in the absence of caspase-8 activity." (PMID 30551590, 2018). "Unlike CASP8 and CTNNB1, which are part of our CONIM list, SPOP did not pass our pan-cancer CNA enrichment filter criteria because the effect of SPOP on CNAs is highly cancer-type-specific." (PMID 27831464, 2016). "Caspase-8 expression was not induced by JQ1 (data not shown), indicating that the mitochondrial apoptosis pathway, rather than the extrinsic pathway, mediates the anti-cancer activity of JQ1 in HCC cells." (PMID 26575167, 2016). "However, caspase-8 knockout was enriched in MC38/MC38-OVA tumors, but not in B16F10 cells, implying that the role of Casp8 may vary among cancer types." (PMID 36635765, 2023). "In many cancer cell lines SAHA initiates cell death by activation of mitochondria-mediated death pathways that are characterized by cytochrome c release and formation of reactive oxygen species (ROS), without the activation of key caspases such as caspase-8 or caspase-3." (PMID 30583560, 2018). "In Pcys-treated gut cell lines, caspase 8 (apoptosis extrinsic pathway) but not caspase 9 (apoptosis intrinsic pathway) is activated after 3 hours through P38 phosphorylation (90 min), emphasizing the potency of lowbush blueberry Pcys to eradicate gut TRAIL-resistant cancer cells." (PMID 26180579, 2015).
tumor (711 papers, 2001 to 2026). "We showed CASP8 mutations alter pro‐caspase‐8 and active caspase‐8 levels in tumour lysates as evident from western blot assays." (PMID 40621643, 2025). "For example, a high impact variant resulting in a premature stop codon (p.Glu89*) in CASP8 was observed in the Oncopig HCC tumor." (PMID 40340757, 2025). "These oncogenic somatic mutations occurred significantly (p = .0331) more frequently in tumours with CASP8 mutations (45.45%) than among the remaining (12.5%)." (PMID 40621643, 2025). "Previous studies revealed that Caspase 8 is often lost or mutated in various tumor types, making it a common target for immune evasion." (PMID 39868264, 2025). "It is worth noting that CFLAR, an analog of Caspase 8, is associated with cell migration, similar to Caspase 8, which has been linked to migration in both normal and tumor cells." (PMID 40362257, 2025). "In contrast, CASP8‐mutated tumours (enriched for co‐occurrence of other oncogenic‐mutations) showed significantly (p = .026) higher infiltration of TILs (median = 9.98%), than the rest (0.17%)." (PMID 40621643, 2025). "Increased caspase-8 activity in various tumor cell lines has also been associated with increased caspase activity, motility and aggressiveness." (PMID 38877579, 2024). "Elevated levels of SERPINB3 in P66shc-downregulated tumors inhibit Caspase-8 activity, rendering tumor cells more susceptible to necroptosis." (PMID 38918587, 2024). "On treatment with a chemical carcinogen deletion of Caspase-8 resulted in increased reactive oxygen species and tumor susceptibility." (PMID 39625985, 2024). "While TNFR1, FADD and caspase-8 have been crucially implicated in the killing of tumor cells by CD8+ T cells and NK cells, the LUBAC components were found to antagonize the latter." (PMID 38020877, 2023). "Another study focusing on caspase 8 revealed that inactivating caspase 8 mutations rendered HNSCCs particularly susceptible to birinapant + RT, and this phenomenon was dependent on tumor cells maintaining RIP3 expression." (PMID 37132167, 2023). "Co‐expression analysis of the TCGA HNSCC clinical dataset for FASLG expression in CASP8 mutated samples supports our proposal that tumour cells are protected from FasL‐mediated apoptosis." (PMID 37443405, 2023). "Mechanistically, Casp8 deficiency or pharmacological disruption results in impaired ecto-calreticulin transition in tumor cells, which in turn hampers antigen presentation in draining lymph nodes." (PMID 36635765, 2023). "We observed that tumours with CASP8 mutations had higher mean FASLG expression, suggesting that the OSCC lines were resistant to FasL‐mediated apoptosis." (PMID 37443405, 2023). "An increasing number of studies have confirmed that CASP8 is associated with tumor growth and invasion, angiogenesis, metastasis, therapeutic resistance, and poor clinical outcomes." (PMID 35659304, 2022). "Surprisingly, Cur@affi-F/GQs significantly enhance the expression and activity of apoptosis-associated proteins in Bcl-2/Bax-caspase 8, 9-caspase 3 apoptotic pathway, which is the main factor in the death of tumor cells induced by FUdR." (PMID 35215023, 2022). "CTLA-4 resides on tumor cells at various densities and triggers apoptosis associated with the sequential activation of caspase-8 and caspase-3." (PMID 35281086, 2022). "To better understanding the impact of CASP8 on tumor behavior in BLCA, we also assessed the association between the expressions of CASP8 with clinical characteristics." (PMID 35928267, 2022). "In a B-cell lymphoma tumor model, the loss of caspase-8 was not only found to increase lymphomagenesis, but it also resulted in an increase in chromosomal instability." (PMID 35741016, 2022). "The gene CASP8 encoding caspase-8 is mutated in 10% of HNSCC tumours analysed by The Cancer Genome Atlas34." (PMID 33602906, 2021).
tumor (continued). "Chemotherapy–birinapant combinations were most effective in reducing Caspase 8-deficient xenografts tumor growth rate by 2/3 after 8 weeks (*p < 0.05 compared to vehicle)." (PMID 34088893, 2021). "The DR4/DR5 and TRAIL complex activates programmed cell-death signaling by stimulating the FAS-associated death domain protein (FADD) and the caspase-8 proenzyme, leading to apoptosis and tumor cell death." (PMID 34641520, 2021). "Epigenetic mechanisms are also implicated in the inactivation of caspase-8 during tumor development and progression." (PMID 33916780, 2021). "Since it has been demonstrated that p62 overexpression leads to caspase-8-dependent apoptosis, our results suggest that inhibition of autophagy caused by AdoMet leads to an increase of apoptosis, promoting tumor cell death." (PMID 33374288, 2020). "CASP-8 gene is primarily a tumor suppressor gene encoding procaspase-8 protein found on chromosome 2q33-34." (PMID 35047986, 2020). "Other apoptosis-associated proteins, such as TFIP8, a tumor suppressor that regulates TNF-mediated apoptosis via inhibition of caspase-8 were also upregulated in HS578T/NOD1." (PMID 30791886, 2019). "Caspase-8, the protease encoded by CASP8 gene, plays a dual role in programmed cell death, which in turn has an important role in tumor cell death and drug resistance." (PMID 30775178, 2019). "CASP8 mutations are implicated in subverting apoptosis induced by lymphocytes; they are enriched in tumours with high immune cytolytic activity and likely reflect an increased selective pressure exerted by the presence of adaptive immune cells." (PMID 30104673, 2018). "The functionally-verified immune-resistance genes that were disproportionally mutated in hot tumours included those involved in antigen presentation (B2M and HLA-A), apoptosis (CASP8) and interferon signalling (JAK1)." (PMID 30104673, 2018). "The tumor cells were also susceptible to apoptosis under VU treatment, which was revealed by activation of caspase-8/9/3 via cleaving and disruption of the Bcl-2/Bax expression balance." (PMID 29867331, 2018). "It has also been reported that many CASP8 mutations, while loss of function in some aspects, result in increases in nuclear factor kappa B signaling and general tumor inflammatory state." (PMID 28749946, 2017). "All these data suggest that glucose deprivation induces caspase-8-dependent apoptosis in diverse human tumor lines with either an intact or a deficient mitochondrial pathway." (PMID 28242652, 2017). "For example, the association between FAT1 mutation and overall survival in HNSCC differs according to the HPV status of the tumour, and loss of Caspase 8 not only has cell intrinsic effects but can also trigger inflammation." (PMID 27693639, 2016). "We show that loss of function mutations in FAT1 (an atypical cadherin) and CASP8 (Caspase 8) frequently occur in the same tumour." (PMID 27693639, 2016). "Both cisplatin and doxorubicin suppressed tumor cells by activating P21-associated cell cycle arrest and caspase-3 dependent apoptosis via caspase-8 or caspase-9 pathways." (PMID 26557666, 2015). "This strongly suggests that caspase-8 possesses tumor suppressor functions and indeed caspase-8 deficiency facilitates cellular transformation." (PMID 24931006, 2014). "Loss or downregulation of caspase-8 has been proposed as a possible mechanism of apoptosis resistance in tumor cells." (PMID 24209510, 2013). "Other clinical findings concerning tumor-related genes included an association of methylation of CASP8 with age and tumor size and an inverse correlation between RASSF1A methylation and clinical growth index." (PMID 22567403, 2012).